MTHFD1L (methylenetetrahydrofolate dehydrogenase (NADP+ dependent) 1 like)
Diseases named in the same sentence as MTHFD1L in open-access papers (continued):
Sharing a sentence is not in itself a finding about the gene and the disease.
spina bifida (1 paper, 2016). A congenital neural tube defect in which vertebrae are not fully formed. "Nevertheless we cannot rule out a potential contribution of reduced Mthfd1L expression to spina bifida in the ct strain, acting to modify the Grhl3 effect, as we previously observed for a Lmnb1 variant (Deletion 18: 56909394) present in the ct genetic background." (PMID 26924399, 2016).
tumor (24 papers, 2018 to 2025). "For instance, in cells overexpressing miR–221, we observed an upregulation of FRAT2, AMD1, and MTHFD1L, genes linked to tumor progression, severity, invasiveness, and worse prognosis." (PMID 38339342, 2024). "Six sex-specific, Esr1-dependent transcripts–A1bg, Fmo3, Cabyr, Cspg5, Mthfd1l, Tff3–are strongly implicated in hepatocarcinogenesis based on their expression, prognostic power, or oncogenic/tumor suppressive properties." (PMID 34068249, 2021). "Studies have shown that mitochondrial enzymes involved in the one-carbon pathway, namely SHMT2, MTHFD2, and MTHFD1L, affect the proliferation rate of tumor cells." (PMID 38881906, 2024). "Earlier studies have reported that MTHFD1L plays a key role in tumor development by dysregulating the folic acid cycle." (PMID 34908119, 2022). "In the present work, to uncover the MTHFD1L expression variations across different cancers, we analyzed a large tumor sample size paired with controls from different reliable online databases through a comprehensive bioinformatics approach." (PMID 34908119, 2022). "The results showed that the expression of circ-MTHFD1L was significantly upregulated in tumor tissues compared with matched normal tissues." (PMID 35459186, 2022). "Its overexpression was related with unfavorable prognosis and tumor metastasis, and it also was involved in the regulatory action of MTHFD1L to OS." (PMID 33146000, 2021). "Numerous previous studies have reported that MTHFD1L has formyltetrahydrofolate synthase activity and participates in the folic acid cycle, and plays a vital role in supporting tumor growth." (PMID 33605411, 2021). "MTHFD1L enhanced proliferation in some cancer tissues, as knock down of MTHFD1L slowed the tumor growth." (PMID 32111066, 2020). "The anti-tumor effects of MTHFD1L knockdown on TSCC tumorigenesis were evaluated in vitro and in vivo." (PMID 31867267, 2019). "In our study, the immunohistochemical results demonstrated that the MTHFD1L protein was expressed at much higher levels in the tumor tissues than in the matched ANTs." (PMID 31867267, 2019). "It is well-known that MTHFD1L is overexpressed in multiple solid cancers, demonstrating that the folate cycle plays an important role in tumor metabolism and in accelerating tumor growth." (PMID 31867267, 2019). "It has been reported that MTHFD1L overexpressed in many types of cancers, and promoted tumorigenesis and tumor progression." (PMID 31867267, 2019). "In untreated patients, the expression of GGH and MTHFD1L was significantly higher in tumour tissue compared to mucosa." (PMID 30269276, 2018). "After LV treatment, a significant positive correlation was seen between the folate concentration and expression of all genes, except MTHFD1L, in tumour tissue." (PMID 30269276, 2018). "However, some CRGs with CNV loss, such as IDH2, MTHFD1L, and ABCE1, showed upregulated mRNA expression, while other CRGs with CNV gain, such as TPK1, showed downregulated mRNA expression between tumor and normal samples." (PMID 36505852, 2022). "We then used the same approach to calculate the ratios of reads mapped to the terminal exon of the short isoform and the terminal exon of the full-length MTHFD1L isoform for each sample and then compared the mean of the ratios across all normal samples to that for all tumour samples." (PMID 31147722, 2019). "We observed that in the CAL-27 MTHFD1L knockdown tumor biopsies." (PMID 31867267, 2019). "It is hypothesized that MTHFD1L promotes tumor metastasis by increasing antioxidant stress." (PMID 32368304, 2020). "Our results showed that MTHFD1L could promote the migration ability of tumor." (PMID 32368304, 2020).
tumor (continued). "In view of this, we explored the possibility of MTHFD1L as a potential biomarker of LIHC prognosis, and analyzed the interaction between tumor immune infiltration and MTHFD1L expression in LIHC." (PMID 33605411, 2021). "The expression of MTHFD1L in CRC was positively correlated with the degree of tumor differentiation, TNM classification, tumor invasion, lymph node metastasis, and distant metastasis." (PMID 32368304, 2020). "After LV injection, the expression of FPGS, GGH, MTHFD1L, and SLC19A1/RFC-1 was significantly higher in tumour tissue compared to the mucosa." (PMID 30269276, 2018). "The results of the study showed that tumour tissue of untreated patients had higher expression of FPGS, GGH, MTHFD1L, and SLC19A1/RFC-1 compared with mucosa, whereas expression of ABCC3/MRP3 and SLC46A1/PCFT was higher in mucosa compared with tumour." (PMID 30269276, 2018). "After LV injection, a significantly higher gene expression level of GGH, MTHFD1L, SLC19A1/RFC-1, and FPGS was seen in tumour tissue compared to mucosa." (PMID 30269276, 2018). "Among them, MTHFD1L and GLS have been reported to be tumor-promoting in HCC32,33." (PMID 35710796, 2022). "As expected, the MTHFD1L knockdown group had slower tumor growth and lower tumor weight than the negative control group (P < 001, for control vs. knockdown groups)." (PMID 31867267, 2019). "As a result of tumor immunity analysis, MTHFD2L expression was found to be negatively related to the Estimate-Stromal-Immune score in OSCC; however, there was no statistical significance between the Estimate-Stromal-Immune score and MTHFD1, MTHFD1L, or MTHFD2 in OSCC." (PMID 35693982, 2022). "However, there was no statistical significance between MTHFD1, MTHFD1L, or MTHFD2 and the tumor microenvironment in OSCC." (PMID 35693982, 2022).
cancer (22 papers, 2016 to 2025). A tumor composed of atypical neoplastic, often pleomorphic cells that invade other tissues. "MTHFD1L, a mitochondrial protein with tetrahydrofolate synthase activity, not only plays an important role in supporting cancer growth but also increases susceptibility to targeted therapy." (PMID 36544763, 2022). "We identified hnRNPC as a critical regulator for the establishment of cancer characteristic profiles in a subset of genes including MTHFD1L, which has been strongly linked to cancer progression." (PMID 31147722, 2019). "Interestingly, MTHFD1L also has been associated with redox homeostasis in cancer and, as we have demonstrated, one of the main consequences in cancer development in the liver with lipid overloaded is the disruption of redox balance." (PMID 33917315, 2021). "Silencing MTHFD1L can increase oxidative stress, making cancer cells sensitive to sorafenib (a targeted therapy for HCC)." (PMID 38739940, 2024). "Studies show that significant increases in MTHFD2 and MTHFD1 are associated with poorer survival rates, and MTHFD1L (another enzyme in the folate cycle) aids in the production and accumulation of NADPH, greatly alleviating oxidative stress in cancer cells." (PMID 38739940, 2024). "For example, any drug targeting mitochondrial methylenetetrahydrofolate dehydrogenase (MTHFD1L) cancer cells can compensate using cytoplasmic MTHFD1." (PMID 37627515, 2023). "We detected the remarkably higher MTHFD1L overexpression in 24 major subtypes of human cancers matched with controls." (PMID 34908119, 2022). "This implies that MTHFD1L plays a significant role in the development and progression of these cancers." (PMID 34908119, 2022). "Deficiency in genes responsible for supplying cancer cells with the substrates for de novo glutathione synthesis (SLC7A11, SHMT2, and MTHFD1L), as well as the enzymes required to synthesize glutathione (GCLC and GCLM), augments the activity of eprenetapopt." (PMID 36103522, 2022). "Results of the analysis showed a significant (P<0.05) up-regulation of MTHFD1L in all 24 major cancer tissues relative to controls." (PMID 34908119, 2022). "In the current study, we explored MTHFD1L expression as a shared potential cancer biomarker in 24 major human cancer subtypes." (PMID 34908119, 2022). "Further research is required to fully establish the contribution of each specific gene, including four outstanding genes (Slc41a3, Fabp5, Mthfd1l and Igdcc4) with clinical relevance in human cancer." (PMID 33917315, 2021). "Our approach using distinct cell lines identified characteristic APA profile changes in several cancer relevant genes including SMAD3, PA2G4 and MTHFD1L and linked the latter two to the de-regulation of hnRNPC in metastatic site-derived cells." (PMID 31147722, 2019). "The overexpression of both MTHFD1L and MTHFD2 has been reported in cancer cells where it is associated with greater mortality." (PMID 31147722, 2019). "From this analysis, we conclude that we have identified a number of cell type specific CR-APA events and this includes genes, most notably MTHFD1L, that have a high relevance for cancer progression." (PMID 31147722, 2019). "In addition to its toxicity in MTHFD2-expressing cancers, we also discover that TH9619 has a potent antitumorigenic effect on cancers deficient in mitochondrial 1C enzymes (MTHFD2 and MTHFD1L) by blocking purine synthesis." (PMID 37012496, 2023). "For example, increased expression of rate-limiting one-carbon metabolism enzymes such as SHMT2 and MTHFD1L provides activated methyl groups that are needed for nucleotide biosynthesis and viral replication; these mechanisms have been studied in cancer, and inhibitors are available." (PMID 35891396, 2022). "Modulating MTHFD1L expression using different chemotherapeutic drugs may be a promising future treatment option for these cancer patients." (PMID 34908119, 2022).
cancer (continued). "Therefore, it is reasonable to assume that MTHFD1L promotes the proliferation of cancer cells by promoting the biosynthesis of nucleotides in the folate cycle." (PMID 32368304, 2020). "In this study, MTHFD1L was highly expressed in TSCC tissues compared with adjacent non-carcinoma tissues (ANTs), and its high expression was also associated with advanced clinical TNM stage and poor prognosis, demonstrating that MTHFD1L could be a prognostic indicator in TSCC." (PMID 31867267, 2019). "Studies show that MTHFD1L contributes to the production and accumulation of NADPH to levels that are sufficient to combat oxidative stress in cancer cells." (PMID 39484215, 2024). "MTHFD1L, an enzyme in the folate cycle, can be activated by NRF2 and contributes to the production and accumulation of NADPH to combat oxidative stress in cancer cells." (PMID 37328616, 2023). "In view of the results of our analysis, a significant (P<0.05) overexpression of MTHFD1L was also observed in BLCA, HNSC, KIRP, LUAD, and UCEC patients of different clinicopathological features including different cancer stages, race, gender, and age." (PMID 34908119, 2022). "Prior to our knowledge, this research is the first to report a shared biomarker role of MTHFD1L in BLCA, HNSC, KIRP, LUAD, and UCEC, suggesting it as a potential therapeutic candidate in the treatment of cancer." (PMID 34908119, 2022). "Via current research, we have noted the remarkable up-regulation of MTHFD1L in BLCA, HNSC, KIRP, LUAD, and UCEC patients of different clinicopathological features (different cancer stages, patients races, genders, and age groups)." (PMID 34908119, 2022). "As a result, a significant up-regulation in MTHFD1L expression was also detected in BLCA, HNSC, KIRP, LUAD, and UCEC patients stratified by different cancer stages, races, genders, and ages." (PMID 34908119, 2022). "To verify these findings, we analyzed the levels of MTHFD1L mRNA and protein expression separately in TSCC tissues (T) and adjacent non-carcinoma tissues (ANTs)." (PMID 31867267, 2019). "Examination of the gene expression of 1425 metabolic enzymes across NCI-60 cancer cell lines revealed that enzymes of glycine metabolism (including SHMT2, MTHFD2 and MTHFD1L) are highly expressed in rapidly-proliferating cancer cells." (PMID 27391339, 2016). "Collectively, these findings highlighted that MTHFD1L overexpression is involved in the initiation and progression of BLCA, HNSC, KIRP, LUAD, and UCEC; therefore, current research is mainly focusing on these five cancer subtypes." (PMID 34908119, 2022). "Expression of three target genes (H2AFX, RUNX3 and MTHFD1L) of miR-133a and one target gene (FYB) of miR-206 was upregulated while expression of these two miRNAs (miR-133a and miR-206) were significantly downregulated in cancer tissues." (PMID 27597234, 2016). "Next, to check whether MTHFD1L higher expression has any effect on the overall survival (OS) duration of the 24 types of cancer patients or not, we used KM plotter and GEPIA tools for OS analysis." (PMID 34908119, 2022). "Furthermore, MTHFD1L effect on the OS of BLCA, HNSC, KIRP, LUAD, and UCEC patients and its hypomethylation have also confirmed MTHFD1L usefulness as a novel potential biomarker of these cancers." (PMID 34908119, 2022). "Altogether, our data suggested that MTHFD1L might have a significant contribution to the development and progression of BLCA, HNSC, KIRP, LUAD, and UCEC, thus the next part of our study will mainly focus on the unique role of MTHFD1L in these five types of human cancers." (PMID 34908119, 2022).
adenocarcinoma (1 paper, 2019). A common cancer characterized by the presence of malignant glandular cells. "We show that a reduction of hnRNPC levels in metastatic-derived SW620 cells reverts the APA profile of several genes including MTHFD1L to those characteristic for normal- and adenocarcinoma-derived cells." (PMID 31147722, 2019).
cardiovascular disorder (1 paper, 2020). A disease involving the cardiovascular system. "The purpose of this study was to investigate the effects of the SH2B3, MTHFD1L, GGCX, and ITGB3 gene variants on the efficacy of warfarin treatment and its effects on the risk of cardiovascular disorders in Jordanian patients." (PMID 32916786, 2020).
MTHFD1L also shares sentences with these, for which no sentence is quoted: head and neck squamous cell carcinoma (2 papers); acute myeloid leukemia (1); Anophthalmia (1); bipolar disorder (1); cystic kidneys (1); esophageal (1); esophageal squamous cell carcinoma (1); heart disease (1); hyperthyroidism (1); infection (1); Micrognathia (1); mood disorder (1); neurologic disease (1); pancreatic neuroendocrine neoplasm (1); schizophrenia (1); tongue cancer (1).